PCNA (proliferating cell nuclear antigen)
Diseases named in the same sentence as PCNA in open-access papers (continued):
Sharing a sentence is not in itself a finding about the gene and the disease.
tumor (continued). "PCNA, which is a marker of proliferation, was down-regulated in tumor tissues in SYY treated group (HCCLM3 + HSC 22880 ± 1510 vs. HCCLM3 + HSC + SYY 15240 ± 1050, P = 0.0143)." (PMID 26517671, 2015). "Human HLTF, implicated in error-free replication of damaged DNA and tumour suppression, exhibits a HIRAN domain, a RING domain, and a SWI/SNF domain facilitating DNA-binding, PCNA-polyubiquitin-ligase, and dsDNA-translocase activities, respectively." (PMID 26350214, 2015). "The limb tumor in particular showed rapid cell proliferation, with > 90% of the cells showing increased PCNA staining." (PMID 26097888, 2015). "The immunohistochemical analysis showed a significant decrease in Ki67 and proliferating cell nuclear antigen (PCNA) expression in tumours derived from mutant cells compared with those derived from wild-type cells." (PMID 26300397, 2015). "Western blotting analysis of tumor tissues showed that the protein expression of proliferating cell nuclear antigen and ENTPD5 was decreased but that of Caspase 3 was increased in ENTPD5-KD group of mice compared with control groups." (PMID 25794010, 2015). "The expression level of PCNA in the tumor tissue of mice in the Gemcitabine+iRGD group was significantly reduced compared with that of mice in the Gemcitabine group." (PMID 26066322, 2015). "Consistent with the reduction in tumor growth, PCNA staining was also decreased in 100 mg/kg SH-treated tumors." (PMID 25749075, 2015). "We found that levels of molecules cyclin D1, CDK4, E2F1 and PCNA were increased significantly in the tumor lysates of metformin administered mice as compared to control, while p21 level was diminished." (PMID 26484566, 2015). "We investigated the individual and combined effect of PROG (5 and 80 μM) and TMZ (100 μM, the best anti-tumor dose) exposures on the proliferation of U87MG and U118MG cells using the expression of PCNA as a marker of tumor cell proliferation." (PMID 26110872, 2015). "In general, however, those compounds that significantly increased PCNA trimer stability were most potent at inhibiting tumor cell growth." (PMID 25729582, 2015). "The effects of α-tomatine and curcumin on the proliferation of PC-3 tumors were investigated by determining the expression of proliferating cell nuclear antigen (PCNA) in tumor cells." (PMID 26630272, 2015). "To investigate the inhibitory effect of OD on the proliferation in tumor cells, we performed immunostaining in PCNA, which is a cell proliferation marker." (PMID 25852766, 2015). "In xenografts, p-NO-ASA inhibited tumor growth by inhibiting proliferation (PCNA and tumor volume), inducing apoptosis (TUNEL positive cells) and reducing NF-κB expression." (PMID 26184135, 2015). "These peptides and small molecule induce cytotoxicity or inhibit tumor growth at micromolar concentrations and are less potent in comparison with the PCNA-Is identified in our studies." (PMID 25729582, 2015). "A good correlation between PCNA positive cells and tumor weight in individual mice was found (r = 0.72)." (PMID 26630272, 2015). "Overall, this study led to the identification of 14 compounds with superior PCNA stabilization and inhibition of tumor cell growth to PCNA-I1, and the most potent analogs from the scaffold A class." (PMID 25729582, 2015). "The immunohistochemistry analysis of tumor section by H&E, and by proliferation antigens against PCNA staining revealed that SVT inhibited tumor growth." (PMID 26061816, 2015). "The cell proliferation marker PCNA was expressed in all tumor specimens, and the Pi of all tumor specimens ranged from 0.8 to 85.3% (33.06 ± 20.93%)." (PMID 25922553, 2015). "In this study, more than 50% of the tumor cells were positive for nuclear expression of 14-3-3γ, Myc, and PCNA." (PMID 26427597, 2015).
tumor (continued). "In conclusion, we have validated that PCNA-I1 targets PCNA and discovered several PCNA-I1 analogs superior to PCNA-I1 in stabilizing PCNA trimer structure and inhibiting tumor cell growth." (PMID 25729582, 2015). "Reductions in tumor burden were accompanied by diminished PCNA expression and enhanced numbers of TUNEL-positive apoptotic cells." (PMID 26413810, 2015). "The gene and protein levels of PCNA showed that the rate and activity of tumor cell proliferation was reduced by ASX (100 μM, 200 μM, and 300 μM) treatment." (PMID 26404320, 2015). "As a tumor marker, PCNA is a kind of cell cycle protein, found in the nucleus, which plays an important role in the synthesis of DNA." (PMID 26495015, 2015). "Tumor cells express high levels of PCNA, identifying it as a potentially ideal target for cancer therapy." (PMID 25729582, 2015). "To further confirm the expression level of PCNA, we extracted the total protein from the tumor tissues in each group." (PMID 26066322, 2015). "Western blot analysis of tumor tissue harvested from EphA4−/−EphA7−/−Smo, EphA4+/−EphA7−/−Smo, and EphA4+/+EphA7−/−Smo mice revealed expression of p-Akt and PCNA that correlated with actual tumor size." (PMID 26345456, 2015). "YC also exhibited the inhibition of the expression of the proliferation biomarkers Ki-67 and proliferating cell nuclear antigen (PCNA) in tumor tissues." (PMID 26656173, 2015). "Six SAR compounds, SAR-2, SAR-6, SAR-7, SAR-24, SAR-25, SAR-26, and SAR-27, had similar or stronger effects on tumor cell growth and PCNA trimer stability when compared to PCNA-I1." (PMID 25729582, 2015). "Histological analysis of tumor regions showed that proliferating (PCNA-positive) cells were more abundant in CUL4B transgenic mice than in littermate control mice." (PMID 25945838, 2015). "We also examined the effect of AP-2α knockdown on the expression of PCNA, an important indicator for tumor growth." (PMID 25669978, 2015). "For this, serial sections were subjected to PCNA immunostaining as above, with simultaneous hematoxylin staining of isotype control sections, and the percentage of PCNA-positive cells in tumor areas was assessed as a measure of cellular proliferation rate." (PMID 26147201, 2015). "Tumor and intratumoral stroma areas were discriminated based on proliferating cell nuclear antigen immunoreactivity and inflammatory infiltration was assessed in intratumoral stroma areas." (PMID 26147201, 2015). "CRISPR-Ptch1 tumours (TF and EP) were also highly proliferative (PCNA-positive) and positive for the granule cell marker Atoh129, with considerably fewer postmitotic cells (p27Kip1)." (PMID 26067104, 2015). "PCNA staining by immunohistochemistry showed a higher proliferative rate in tumors co-injected with CSC-EV-stimulated MSCs (4.7 fold increase) than in tumor containing unstimulated MSCs." (PMID 25797265, 2015). "Promotion of tumourigenesis by Wnt/β-catenin signaling was further confirmed by TUNEL assay and proliferating cell nuclear antigen (PCNA) immunohistochemistry using tumor xenografts." (PMID 26202299, 2015). "These compounds, SAR-6 and SAR-24, were selected based on their potent inhibitory effects on tumor cell growth, PCNA trimer stabilization, and potentially improved solubility (cLogP)." (PMID 25729582, 2015). "The 2-DG group tumors, relative to control tumors, had significantly reduced cellular proliferation (PCNA staining), which corresponds to the BrdU assay results suggesting a decrease in the proliferation of tumor cells by 2-DG." (PMID 26135741, 2015). "To further investigate the association of PDCD10 expression and the status of tumor cells, i.e., proliferation or apoptosis, we performed double staining of PDCD10/PCNA and PDCD10/caspase 3 (active form)." (PMID 26490252, 2015). "A dose-dependent decrease in proliferating nuclear cell antigen (PCNA), a marker of proliferation and increase in the expression of cleaved caspase 3, an apoptosis marker was observed in both tumor xenografts." (PMID 26435478, 2015).
tumor (continued). "The anti-tumor action of vernodalin was further confirmed by examining cell proliferative markers, PCNA and Ki67 in the LA7-induced mammary gland tumor model." (PMID 26643256, 2015). "Increased proliferation was also observed during tumor progression in the mycAG fish, as demonstrated by the PCNA staining in Fig. 2D1–D4 and 2E." (PMID 25612309, 2015). "The effects of TPA and DDTC on PANC-1 tumor growth were investigated by determining the expression of PCNA in the tumor cells." (PMID 25847449, 2015). "According to the results presented above, PFTK1 was positively correlated with PCNA, Ki-67 expression and tumor grade, which were cells proliferation marker." (PMID 26488471, 2015). "Next, qRT-PCR analysis of UCA1 expression and immunostaining analysis of proliferating cell nuclear antigen (PCNA) protein expression were performed in resected tumor tissues." (PMID 25760077, 2015). "The statistical analysis of PCNA and Ki67 indicated a significant reduction in tumor cells after FALHE treatment." (PMID 25996383, 2015). "The expression of PCNA reflects the proliferation activity of cellular and is a reliable index for evaluating tumor cell proliferation." (PMID 26376762, 2015). "Knockdown of Cx32 significantly suppressed the expression of CD82 and enhanced the expression of PCNA in transplanted tumor tissue." (PMID 25426556, 2015). "A positive correlation was evident between tumor size, p-Akt, and proliferating cell nuclear antigen (PCNA) expression in our transgenic mouse model system, regardless of genotype." (PMID 26345456, 2015). "Our data also support a direct correlation between tumor size, phosphorylation of Akt, and PCNA suggestive of a direct effect on cellular proliferation." (PMID 26345456, 2015). "Co-culturing hMSCs with MCF7 cells increased their growth evidenced by increase in Ki67 and PCNA staining in tumor cells in direct contact with hMSCs niche." (PMID 26204886, 2015). "Overall, TQ reduced the percentage of tumor cells expressing the proliferation marker Ki67, consistent with its effects on PCNA expression in our western blot analysis." (PMID 26552746, 2015). "The present study demonstrated that PCNA was highly expressed in all tumor tissues and that the expression of PCNA was increased in colonic ACF compared with that of normal intestinal glands." (PMID 25329503, 2014). "DACH1 protein abundance was inversely correlated with the expression of PCNA and cyclin D1, tumor grade, and TNM stage." (PMID 25322986, 2014). "PCNA expression can reflect cellular proliferation activity and is used as a reliable index for evaluating the kinetics of tumor cell proliferation." (PMID 25329503, 2014). "The observed lower expression of Ki67 and PCNA in the MFE-296/shFOXA1 group was consistent with the smaller tumor volumes in the mouse tumor xenograft model." (PMID 24512546, 2014). "PCNA expression levels tracked very closely with expression of the smallest isoform, C/EBPβ-3, such that PCNA and C/EBPβ-3 were elevated in the same tumor subset." (PMID 25402211, 2014). "The chemopreventive effects of CAPE and CAPPE were in part associated with the suppression of the PCNA, FASN and MMP-9 proteins in these tumor-bearing animals." (PMID 24960186, 2014). "We next examined the effects of embelin on cell proliferation in tumor tissues derived from control and embelin treated mice using anti-PCNA or anti-Ki67 antibody." (PMID 24694877, 2014). "Proliferating cell nuclear antigen and terminal transferase dUTP nick end labeling were used to detect the apoptosis of the tumor cells." (PMID 25033896, 2014). "IHC analysis of the tumour regions confirmed the reduced expression of TCF4, β-catenin and p68 as well as PCNA in the tumours generated with p68 knockdown cells when compared to the tumours generated with EV control cells." (PMID 25499975, 2014). "There were positive correlations between Ki-67, PCNA LIs, and tumor grade (Ki-67: r = 0.728, P < 0.01; PCNA: r = 0.726, P < 0.01)." (PMID 24741354, 2014).
tumor (continued). "The immunohistochemistry analysis of tumor section by H&E, and by proliferation antigens against PCNA staining revealed that thiacremonone inhibited tumor growth." (PMID 24618722, 2014). "Downregulation of the cell cycle regulatory proteins cyclin D1 and PCNA, biomarkers of the malignant phenotype and tumor progression with increased expression of p21 the most potent CDK inhibitor, underscore the antiproliferative effects of astaxanthin." (PMID 25296162, 2014). "Next, immunostaining analysis of the proliferation marker PCNA was performed in resected tumor tissues." (PMID 24775712, 2014). "Since we observed a significant inhibition of tumor growth following the treatment of SF1126 in the xenograft model, we studied the PCNA index and tumor microvessel density (MDV) in the tumors harvested from the animals treated with SF1126." (PMID 25425962, 2014). "We also showed that both the staining intensity and the number of hyperproliferative Ki-67+ and PCNA+ tumor cells were significantly decreased compared with control (P < 0.05)." (PMID 25098939, 2014). "Nestin expression was significantly associated with those of the proliferative markers, Ki-67 (r = 0.795, P<0.001) and PCNA (r = 0.764, P<0.001), indicative of a role in tumor cell proliferation." (PMID 24498263, 2014). "In the present work, we reported that the disruption of the DNMT1/PCNA/UHRF1 complex acts as an oncogenic event of the tumor transformation of brain (astrocytes), breast, lung and mesothelial cells." (PMID 24637615, 2014). "Tumor sections showed hallmarks of apoptosis and the decreased expression of proliferating cell nuclear antigen (PCNA) and CD31 indicated cytostasis and antiangiogenesis." (PMID 24608973, 2014). "PCNA, an auxiliary protein of DNA polymerase δ located in the nuclei of tumor cells, is known as a cell cycle-related nuclear antigen and is synthesized in late G1 and S phase." (PMID 25364410, 2014). "C-Abl nuclear translocation was associated recently with phosphorylation of PCNA and induction of cell proliferation, AIB1 and tumor formation, and c-Jun or c-Fos and promotion of cell proliferation." (PMID 24789045, 2014). "The western blot analysis revealed that the expression level of PCNA was lower in tumor tissues obtained from GSPs-fed mice than in tumor tissues from control mice." (PMID 25361006, 2014). "In vivo, sorafenib-YC-1 combination significantly suppressed the growth of HepG2 tumor xenografts with decreased cell proliferation and increased apoptosis observed by PCNA and PARP." (PMID 24418169, 2014). "Specifically, the relative value of PCNA expression was significantly decreased by 70% in the tumor burden of HB1.F3.CE and CPT-11 treated mice." (PMID 25544747, 2014). "Research from Zhu C, Cao R, Zhang S-X, Man Y-N and Wu X-Z showed that fucoidan, a sulphated polysaccharide purified from brown algae significantly inhibited the tumour growth and the expression of PCNA." (PMID 25519220, 2014). "We next examined the expression of PCNA in the tumor tissues harvested from vehicle treated and SF1126 treated groups." (PMID 25425962, 2014). "As an indicator for the proliferation activity of tumor cells, PCNA was used to evaluate tumor growth." (PMID 24636138, 2014). "Nevertheless, NKp30 has been shown to recognize a tumor cell ligand of the B7 family, B7-H6 and NKp44 is suggested to recognize proliferating cell nuclear antigen (PCNA), which surprisingly triggers inhibition of NK cells." (PMID 23543707, 2013). "Positive expression of Survivin, PCNA, Ki-67, Caspase-3, Bcl-2, Bax or NS protein are those significant yellow or brown particles were observed within tumor cells." (PMID 23325045, 2013).
tumor (continued). "The expressions of PCNA, Ki-67, Bcl-2, Survivin, NS protein in tumor samples were significantly decreased in P + UTMD group, while those of Bax and Caspase-3 were up-regulated significantly." (PMID 23325045, 2013). "In this study, we have identified interactions between HLA I and PCNA on the extracellular membrane of tumor cell lines, where HLA I and PCNA form a complex ligand recognized by NKp44, resulting in inhibition of NK cell cytotoxic function." (PMID 23527218, 2013). "Qualitative histopathological analysis of PCNA-stained sections revealed a decrease in the number of PCNA-positive cells in the tumor tissue of the MGDG-treated mice compared with that of the vehicle-treated controls (P<0.05 for each dosage)." (PMID 23251235, 2013). "We found that the expression of PCNA in the tumour tissues decreased significantly after treatment with 200 mg/kg fucoidan." (PMID 23737842, 2013). "The cyclin E2 level was much lower in tumor tissues overexpressing miR-26a and the PCNA expression followed a similar pattern." (PMID 24116110, 2013). "PCNA immunostaining of tumor tissues from both the control and CRS groups revealed that CRS promoted HT29 cell growth in nude mice." (PMID 23585898, 2013). "The expression level of SATB1 showed correlation with tumor differentiation and pTNM stage, and SATB1 was also associated with the expression of various biologic markers (including Cyclin D1, MMP-2, NF-κB, PCNA, APC and BRAFV600E)." (PMID 23326301, 2013). "The results presented PCNA-positive staining for tumor cells (93/106) and for duct epithelial cells of the adjacent benign pancreatic tissues (68/106; P<0.01)." (PMID 24116110, 2013). "Immunohistochemical analysis of tumor cell proliferation revealed up to 50 % PCNA-positive cells in sham controls of HAI- and sCHT-treated animals." (PMID 23187934, 2013). "According to our PCNA data, treatment with 60°C lipiodol markedly inhibited tumor growth in the rabbits with VX2 carcinomas compared to those treated with 37°C lipiodol." (PMID 23637861, 2013). "Dual immunofluorescence staining revealed that the expression of TIM-3 was observed in all cell types investigated, including CD68+ macrophages, CD31+ endothelial cells, CK-18+ epithelial cells and PCNA+ tumor cells." (PMID 24137353, 2013). "Time-dependent tumor growth was consistently accompanied with immunoreactivity of an anti-PCNA antibody binding, reflecting cell proliferation in vivo." (PMID 24359579, 2013). "Immunohistochemical analyses revealed that PCNA protein expression was detected mainly in viable VX2 tumor cells." (PMID 23637861, 2013). "PTGS2 and PCNA represent two important molecules for the progression of CC and treatment strategy and increased levels of PTGS2 were associated with enhanced tumor cell proliferation and tumorigenesis." (PMID 23865481, 2013). "In this study, we have identified interactions between PCNA and HLA I on the extracellular surface of tumor cells, which forms a complex ligand for NKp44." (PMID 23527218, 2013). "To this aim, we tested the presence of proliferating cell nuclear antigen (PCNA), a cell marker used in MM patients to evaluate the proliferation of clonal plasma cells, and a parameter which also parallels the tumor histological grade." (PMID 24489445, 2013). "Despite the reduction in tumor size following propranolol administration, tumor sections from both sham and propranolol conditions revealed PCNA expression at the tumor peripheries, indicating active cell division." (PMID 23555867, 2013). "Western blot analysis of lysates from six independent tumor samples indicated that while both markers of proliferation (PCNA and Ki-67) decreased in response to α-tomatine treatment, levels of both markers of apoptosis (cleaved-PARP and caspase-3) increased." (PMID 23437404, 2013). "PCNA-PI was mainly found in the tumor cells and increased with HSP70, HSP86 and HSP84 expression (each P<0.05)." (PMID 23599795, 2013).